PCSK9 (proprotein convertase subtilisin/kexin type 9)
Diseases named in the same sentence as PCSK9 in open-access papers (continued):
Sharing a sentence is not in itself a finding about the gene and the disease.
chronic kidney disease (37 papers, 2016 to 2026). Impairment of the renal function secondary to chronic kidney damage persisting for three or more months. "Since diabetes is a leading cause of chronic kidney disease, the effect of PCSK9 inhibitor alirocumab was investigated in patients with T1DM and T2DM." (PMID 37242602, 2023). "Key genes involved in lipid metabolism and vascular calcification, such as SORT1 and PCSK9, are linked to both coronary atherosclerosis and systemic conditions like chronic kidney disease (CKD) and osteoporosis." (PMID 39518317, 2024). "In certain chronic conditions, such as chronic kidney disease and hypothyroidism, the expression and release of PCSK9 are also increased during the inflammatory process." (PMID 38341813, 2024). "Studies have demonstrated the lipid-lowering effects of PCSK9 inhibitors in patients with chronic kidney disease (CKD), showing good safety and efficacy." (PMID 39148544, 2024). "Some researchers have reported a positive association between plasma PCSK9 and plasma TG in the general population and in individuals with different pathologies such as type 1 and type 2 DM, HIV, chronic kidney disease, or type III hyperlipidemia." (PMID 32403394, 2020). "Case reports suggest that PCSK9 inhibitors may be effective in these groups, but robust randomized trials are needed to confirm their safety and efficacy in end-stage renal disease." (PMID 41546841, 2026). "This could be an advantage of PCSK9 inhibitors in dyslipidemic patients with chronic kidney disease." (PMID 39439648, 2024). "PCSK9 inhibitors are a novel class of lipid-lowering medications, and numerous clinical studies have confirmed their significant role in improving the progression of chronic kidney disease." (PMID 39148544, 2024). "Furthermore, one study showed that plasma PCSK9 concentrations were correlated with triglycerides in patients with chronic kidney disease." (PMID 37892538, 2023). "However, the relevance of lipoprotein(a) lowering by PCSK9 inhibitors in patients with chronic kidney disease has yet to be established." (PMID 35621864, 2022). "In addition, this review will focus on new advances on the effects of PCSK9, both intracellular and extracellular, on metabolic diseases such as liver disease, chronic kidney disease (CKD), and neurodegenerative disorders." (PMID 35323658, 2022). "Future trials on chronic kidney disease and PCSK9 inhibitors should investigate the inhibitors' ability to improve kidney functions at all stages of kidney disease while lowering lipid levels and finally analyze the safety in patients with end-stage kidney disease." (PMID 36128564, 2022). "Current literature has pointed that expression and release of PCSK9 depends on other chronic conditions including chronic kidney disease, hyperinsulinemia, hypothyroidism or non-alcoholic fatty liver disease (NAFLD) and also inflammation, which is a significant factor in psoriatic pathogenesis." (PMID 32225075, 2020). "Although patients with severe chronic kidney disease are considered to have a very high cardiovascular risk, the lack of data from clinical studies does not allow the recommendation of anti-PCSK9 medication in this category of patients." (PMID 32375792, 2020). "Serum PCSK9 was measured by ELISA; lipid levels of 251 chronic kidney disease grade 5 (CKD G5) hemodialysis patients and the Framingham predictive instrument were used for predicting cardiac events." (PMID 34270402, 2021).
chronic kidney disease (continued). "Furthermore, a cross-sectional study proved the correlation between plasma PCSK9 levels and soluble markers of endothelial damage (sICAM-1 and sVCAM-1) in patients with chronic kidney disease (CKD)." (PMID 35326219, 2022). "It has recently been suggested that PCSK9 level is correlated with LDL and total cholesterol level in patients with nephrotic syndrome, chronic kidney disease, or dialysis treatment." (PMID 31963408, 2020). "In a study, it was shown that serum PCSK9 level was decreased in chronic kidney disease patients who were on hemodialysis (CLD-HD) and PCSK9 had a positive correlation with LDL-C level." (PMID 29770231, 2018). "Moreover, a systematic review concluded that PCSK9 inhibitors are safe, reliable, and effective medications for decreasing LDL cholesterol levels in patients with chronic kidney diseases." (PMID 37242602, 2023).
breast cancer (36 papers, 2018 to 2026). A primary or metastatic malignant neoplasm involving the breast. "The discovery of the PCSK9 rs562556 variant as a driver of breast cancer metastasis marks a significant milestone in cancer research." (PMID 39872986, 2025). "The identification of the V474I variant as a hypermorphic driver of these processes underscores the importance of germline genetics in shaping metastatic outcomes and provides a compelling rationale for targeting PCSK9 in high-risk breast cancer patients." (PMID 39872986, 2025). "A specific missense variant of PCSK9, rs562556 (V474I), has recently been implicated in breast cancer metastasis, shedding light on the hereditary underpinnings of this lethal process." (PMID 39872986, 2025). "The common missense variant rs562556 in the proprotein convertase subtilisin/kexin type 9 (PCSK9) gene promotes breast cancer metastasis and is associated with reduced patient survival." (PMID 40027151, 2025). "Our findings reveal that elevated PCSK9 expression is associated with improved OS in breast and ovarian cancers, particularly in Luminal B breast cancer subtypes." (PMID 40576911, 2025). "Genetic variants of PCSK9 that increase LDL levels were associated with a higher risk of breast cancer, while LDL-lowering variants, resembling the effects of PCSK9 inhibitors, showed a significant correlation with a reduced risk of developing breast cancer." (PMID 40362754, 2025). "Given the known role of adipose tissue in cancer initiation and progression, and considering that adiponectin was a risk biomarker for breast cancer in the same cohort, we assessed the relationship between PCSK9 and the adipokines adiponectin and leptin." (PMID 38611089, 2024). "PCSK9 associations with biomarkers linked to breast cancer risk were assessed on blood samples collected at baseline." (PMID 38611089, 2024). "And some breast cancer patients showed that women with higher levels of PCSK9 had a higher risk of developing metastatic disease." (PMID 37860186, 2023). "Genetically proxied inhibition of HMG-CoA reductase and NPC1L1 was significantly associated with lower odds of breast cancer, while genetically proxied inhibition of PCSK9 was associated with reduced risk of prostate cancer." (PMID 35151363, 2022). "Lowered LDL-cholesterol due to variants in PCSK9 had a suggestive protective effect on breast cancer risk." (PMID 30262900, 2018). "Lowering of LDL-cholesterol due to variants in PCSK9 was associated with risk-reducing effects on breast cancer occurrence in our study." (PMID 30262900, 2018). "LDL-cholesterol-lowering variants mimicking PCSK9 inhibitors are associated (P = 0.014) with lower breast cancer risk." (PMID 30262900, 2018). "Furthermore, a recent MR study indicates a significant reduction in the risk of breast cancer and lung cancer with PCSK9 inhibitor use." (PMID 38822303, 2024). "In the present study, we first found that genetically proxied inhibition of HMG-CoA reductase and NPC1L1 were significantly associated with lower odds of breast cancer (especially ER-positive breast cancer), while the inhibition of PCSK9 was associated with reduced risk of prostate cancer." (PMID 35151363, 2022). "Genetically proxied inhibition of HMG-CoA reductase and NPC1L1 was significantly associated with lower odds of breast cancer (especially ER-positive breast cancer), while genetically proxied inhibition of PCSK9 was associated with reduced risk of prostate cancer." (PMID 35151363, 2022). "Given that PCSK9 plays an important role in maintaining cholesterolemia, and a potential role in tumor evasion, present results warrant further investigation into a possible association between PCSK9 levels and breast cancer severity in larger cohorts of women." (PMID 36203122, 2022). "In addition, LOF and GOF variants of PCSK9 were associated with lower and higher incidence of breast cancer, respectively." (PMID 34606887, 2021).
breast cancer (continued). "Studies on the risk of breast cancer in correlation with the concentration of lipids in the bloodstream showed that mutations causing a decrease in PCSK-9 activity and, thus, a decrease in LDLc concentration, were associated with a lower risk of this type of cancer." (PMID 33808697, 2021). "A Mendelian randomized grouping experiment proved that genetically elevated LDL-C due to proprotein convertase subtilisin/kexin type 9 (PCSK9) gene mutations could increase the incidence of estrogen receptor-positive breast cancer." (PMID 33096860, 2020). "Given the current lack of clinical data assessing the employment of circulating PCSK9 as a prognostic biomarker in the context of breast neoplastic events, we conducted a prospective analysis within a randomized chemoprevention trial for premenopausal women at risk of breast cancer." (PMID 38611089, 2024). "They should be explored before considering PCSK9, a therapeutic target in patients with breast cancer." (PMID 41870236, 2026). "A recent study identified an association between rs562556 within the PCSK9 gene and breast cancer survival (BCS), suggesting PCSK9 inhibition as an early intervention strategy to prevent metastasizing breast cancer." (PMID 41870236, 2026). "The graphs revealed that high levels of PCSK9 were linked to shorter overall survival (OS) and distant metastasis‐free survival (DMFS) in all breast cancer patients and TNBC patients." (PMID 40192514, 2025). "PCSK9 inhibitors, originally developed for hypercholesterolemia, have shown promise in preclinical models of breast cancer." (PMID 39872986, 2025). "Through a series of elegant experiments, the researchers demonstrated that PCSK9 promotes metastasis by downregulating LRP1 on the surface of breast cancer cells." (PMID 39872986, 2025). "In vitro experiments using low-attachment culture conditions showed that recombinant PCSK9 significantly increased the proliferation of breast cancer cells." (PMID 39872986, 2025). "The discovery of PCSK9’s role in breast cancer metastasis opens new avenues for therapeutic intervention." (PMID 39872986, 2025). "Genetic studies have demonstrated that LDL-cholesterol-lowering variants in PCSK9, responsible for reduced levels of LDL, were associated with either a risk-reducing or a neutral effect on breast cancer." (PMID 38611089, 2024). "In line with this evidence, pharmacological inhibition of PCSK9 improved breast cancer outcomes in BALB/c mice bearing 4T1 breast cancer." (PMID 38611089, 2024). "Previous research has shown that inhibiting PCSK9 can be effective in various cancers, including lung, colorectal, breast cancers, suggesting its broad potential in oncology." (PMID 38760735, 2024). "Previous observational studies have shown that statins, ezetimibe, and PCSK9 inhibitors have protective effects against breast cancer and prostate cancer." (PMID 35151363, 2022). "PCSK9 levels were significantly higher in women with stage III breast cancer compared to age-matched counterparts presenting a benign lesion (95.9 ± 27.1 ng/mL vs. 78.5 ± 19.3 ng/mL, p < 0.05, n = 14)." (PMID 36203122, 2022). "Herein, we conducted a two-sample MR study to assess the causal associations of several LDL-C-lowering drug targets (HMG-CoA reductase, NPC1L1, and PCSK9) with breast cancer and prostate cancer." (PMID 35151363, 2022). "Considering the key role of PCSK9 on lipid metabolism (hyperlipidemic factor) and immune response (destruction of MHC-I), confirmation of increased PCSK9 levels with breast cancer severity in a larger cohort of patients is indicated." (PMID 36203122, 2022). "Similar roles of PCSK9 have also been observed in other types of cancers, such as human neuroglioma, breast cancer, colorectal cancer and others." (PMID 36552895, 2022).
breast cancer (continued). "The levels of s-PCSK9-Ab were higher in patients with solid cancers such as esophageal cancer, gastric cancer, colorectal cancer, lung cancer, and breast cancer than in HDs." (PMID 34504788, 2021). "We recombined the full-length PCSK9 cDNA into pGEX-4T-1, purified the GST-PCSK9 protein, and examined the s-PCSK9-Ab levels in patients with esophageal cancer, gastric cancer, colorectal cancer, lung cancer, and breast cancer." (PMID 34504788, 2021). "Despite recent discoveries indicating atypical PCSK9 expression in various cancers, such as gastric cancer and breast cancer, inhibiting PCSK9 has been documented to elevate cell surface levels of major histocompatibility complex class I and impede tumor growth in cancer cells." (PMID 38822303, 2024). "Indeed, only one recent study on a small sample size (n = 46) of women with stage III breast cancer has been conducted, reporting increasing levels of PCSK9 with the severity of breast disease." (PMID 38611089, 2024). "Besides breast cancer, the involvement of PCSK9 in cancer development has been described in different tissues." (PMID 38611089, 2024). "Rather, these approaches might be effective in cancer prevention, which may shed light on why vaccination of mice for PCSK9 followed by cancer cell implantation was marginally impactful against melanoma and breast cancer growth." (PMID 36588164, 2023). "Whether the increase in PCSK9 plays an active role in the progression of breast cancer requires further investigation." (PMID 36203122, 2022). "Recently, genetically proxied inhibition of HMG-CoA reductase but not NPC1L1 and PCSK9 was associated with lower odds of epithelial ovarian cancer in MR study, while no such MR study was currently available for breast cancer and prostate cancer." (PMID 35151363, 2022). "Therefore, further well-designed randomized trials are warranted to verify the protective effects of statins and ezetimibe on breast cancer and PCSK9 inhibitors on prostate cancer." (PMID 35151363, 2022). "The expression of PCSK9 is deregulated in different types of cancers, including HCC neuroglioma, breast cancer, colorectal cancer and others, highlighting a major question about the therapeutic strategies that could be adopted to target PCSK9 in these cancers." (PMID 36611859, 2022). "However, there have not been randomized controlled trials designed to study the effects of statins and ezetimibe on breast cancer and PCSK9 inhibitors on prostate cancer." (PMID 35151363, 2022). "AlphaLISA showed that serum anti-PCSK9 antibody (s-PCSK9-Ab) levels were significantly higher in patients with esophageal cancer, gastric cancer, colorectal cancer, lung cancer, and breast cancer than in healthy donors, and patients with esophageal cancer had the highest levels." (PMID 34504788, 2021). "In contrast to the lack of general association between PCSK9 and cancer, in the context of breast cancer, there is an association between loss-of-function carriers and gain-of-function carriers and breast cancer." (PMID 33364976, 2020). "Given the aim of the present study, it is worth considering that the strongest correlation we found was the negative one between PCSK9 and 17-β estradiol (r = −0.294), which was maintained even after partial adjustment for BMI and age (r = −0.251), two risk factors for breast cancer." (PMID 38611089, 2024).
breast cancer (continued). "We found that genetically proxied inhibition of HMG-CoA reductase and NPC1L1 but not PCSK9 were significantly associated with reduced risk of breast cancer (mainly ER-positive breast cancer), while only genetically determined PCSK9 inhibition was associated with low odds of prostate cancer." (PMID 35151363, 2022). "In addition, the influence of hormones, sex differences in immunity, and complexity of the regulatory mechanism in tumor angiogenesis may also contribute to the different roles of stains, ezetimibe and PCSk9 inhibition in breast cancer and prostate cancer." (PMID 35151363, 2022). "Accordingly, it was suggested that PCSK9 expression could be a valuable biomarker for the clinical prognostic outcome of certain types of malignancies, including hepatocellular carcinoma, gastric, kidney, pancreas, and breast cancers." (PMID 34606887, 2021). "LDL-raising variants in PCSK9 were associated with increased risk of breast cancer (OR 1.10, 95% CI, 1.02–1.19, P = 0.014) but not with ER-positive (OR 1.08, 95% CI, 0.99–1.18, P = 0.099) or ER-negative breast cancer (OR 1.13, 95% CI, 0.98–1.30, P = 0.089) at the nominal significance level." (PMID 30262900, 2018). "We further compared the levels of PCSK9 between two TNBC cell lines (MDA‐MB‐231 and MDA‐MB‐468) and three non‐TNBC breast cancer cell lines (UACC‐893, SK‐BR‐3, and MCF7) by qPCR and Western blotting analyses." (PMID 40192514, 2025). "Inhibits PCSK9 secretion and its interaction with LDL receptor, suppressing breast cancer progression." (PMID 38812679, 2024). "The present work aimed to determine plasma levels of PCSK9, ANGPTL3 and Lp(a) in women with benign disease of the breast, stage 0 and stage III breast cancers." (PMID 36203122, 2022). "Considering the strong evidence for PCSK9’s oncogenic involvement, it is surprising that PCSK9 vaccine has no impact on melanoma and only modestly reduces breast cancer growth in murine models." (PMID 36588164, 2023). "Our study was not designed to address the origin of the extra levels of PCSK9 measured in advanced breast cancers." (PMID 36203122, 2022). "Nevertheless, this reveals that the inhibition of PCSK9 by vaccination had no side effects on the breast tumor endpoint and that it could improve breast cancer behavior." (PMID 36552895, 2022). "Since the role, if any, of PCSK9, ANGPTL3, and Lp(a) in cancers has not been fully investigated to date, the current study aims to establish the levels of these lipid-related proteins in breast cancers." (PMID 36203122, 2022).